NDUFV1 (NADH:ubiquinone oxidoreductase core subunit V1)
Description:
Core subunit of the mitochondrial membrane respiratory chain NADH dehydrogenase (Complex I) which catalyzes electron transfer from NADH through the respiratory chain, using ubiquinone as an electron acceptor. Part of the peripheral arm of the enzyme, where the electrons from NADH are accepted by flavin mononucleotide (FMN) and then passed along a chain of iron-sulfur clusters by electron tunnelling to the final acceptor ubiquinone. Contains FMN, which is the initial electron acceptor as well as one iron-sulfur cluster.
Synonyms: UQOR1; CI-51K; CI51KD; MC1DN4
Tractability: Small molecule: an approved drug acts on it; a structure with a bound ligand is known. Antibody: UniProt places it where antibodies can reach, with medium confidence. PROTAC: ubiquitination databases record sites on it; its protein half-life has been measured.
Target class: Enzyme; Oxidoreductase
Gene: Protein-coding gene on chromosome 11 (67,605,653 to 67,612,554, forward strand). Ensembl gene ENSG00000167792.
Subcellular location: Mitochondrion inner membrane
Subcellular location (Human Protein Atlas): Mitochondria; Cytosol
Pathways (Reactome):
Metabolism: Complex I biogenesis; Respiratory electron transport
Metabolism of proteins: Mitochondrial protein degradation
Gene Ontology:
Molecular function: NADH dehydrogenase (ubiquinone) activity; protein binding; 4 iron, 4 sulfur cluster binding; FMN binding; NAD binding
Biological process: mitochondrial ATP synthesis coupled electron transport; mitochondrial electron transport, NADH to ubiquinone; aerobic respiration; proton motive force-driven mitochondrial ATP synthesis; proton transmembrane transport
Cellular component: mitochondrial inner membrane; mitochondrion; respiratory chain complex I
Genetic constraint (gnomAD): Loss-of-function variants: 44 observed, 52.08 expected, observed/expected ratio (o/e) 0.84, 90% interval 0.66 to 1.09. The upper end of that interval is the gene's LOEUF score, 1.09, which puts it in group 4 of 6, group 1 being the genes least tolerant of losing a copy. Missense variants: 580 observed, 667.7 expected, observed/expected ratio (o/e) 0.87, 90% interval 0.81 to 0.93. Synonymous variants: 231 observed, 270.38 expected, observed/expected ratio (o/e) 0.85, 90% interval 0.77 to 0.95.
Gene-disease validity (ClinGen):
ClinGen rates the evidence that NDUFV1 causes each of these diseases.
Leigh syndrome (autosomal recessive): Definitive. A progressive neurological disease defined by specific neuropathological features associating brainstem and basal ganglia lesions.
mitochondrial disease (autosomal recessive): Definitive.
Homologues: Orthologues: chimpanzee NDUFV1 (99% identical), dog NDUFV1 (97% identical), guinea pig NDUFV1 (97% identical), pig NDUFV1 (97% identical), mouse Ndufv1 (96% identical), macaque NDUFV1 (95% identical), rat Ndufv1 (95% identical), tropical clawed frog ndufv1 (86% identical), zebrafish ndufv1 (85% identical), Drosophila melanogaster ND-51 (81% identical), Caenorhabditis elegans nuo-1 (77% identical), Drosophila melanogaster ND-51L1 (72% identical), and 1 more.